LRIG1 (leucine rich repeats and immunoglobulin like domains 1)
Diseases named in the same sentence as LRIG1 in open-access papers (continued):
Sharing a sentence is not in itself a finding about the gene and the disease.
cancer (56 papers, 2010 to 2025). A tumor composed of atypical neoplastic, often pleomorphic cells that invade other tissues. "Leucine-rich repeat and immunoglobulin-like domain (LRIG) 1 is a negative regulator of receptor tyrosine kinases and a tumor suppressor; decreased LRIG1 expression is consistently observed in various types of cancer and is linked to poor patient prognosis." (PMID 37239005, 2023). "Although the LRIG1 plays vital role in cancers, little is known about its association with clinico-patho-physiology characteristics of CRC patients." (PMID 33461538, 2021). "LRIG1 expression is often downregulated in cancer cells, and high expression is associated with improved survival in many cancer types." (PMID 32448168, 2020). "The knockdown of LRIG1 caused the more favorable proliferation of the corresponding 22 cancer cell lines." (PMID 31358815, 2019). "Intriguingly, high LRIG1 expression was associated with superior cancer-specific survival in the PVC patients in our study." (PMID 28841699, 2017). "It has been reported that a recombinant fragment of the LRIG1 ectodomain causes growth inhibition of a panel of carcinoma cells." (PMID 25353163, 2014). "LRIG1 also binds to and inhibits signaling by hepatocyte growth factor receptor (Met), a tyrosine kinase that in many known cancers is mutated or misregulated to promote invasive growth, though its mechanism of inhibition is ubiquitin-independent." (PMID 20502686, 2010). "LRIG1 is found to be upregulated in a variety of HPV-associated cancers." (PMID 36016373, 2022). "For this reason, we posit that other populations of epithelial progenitor cells may exist that can give rise to cancer associated with those sites, specifically LRIG1+ epithelial progenitor cells." (PMID 36016373, 2022). "Although, earlier studies proposed that LRIG1 expression was associated with a good prognosis in terms of overall survival (OS) and might act as a predictive factor for characteristics of cancer patients, whether the LRIG1 expression could predict a lower risk of CRC remains doubtful." (PMID 33461538, 2021). "dCas9-TET1CD-mediated demethylation along with VP64-mediated transcriptional activation increased endogenous LRIG1 expression in breast cancer cells, and reduced cancer cell viability." (PMID 37239005, 2023). "We observe that the memory of an antecedent lesion exacerbates the Lrig1 GL cells response to an oncogenic stimulus, potentially triggering cancer." (PMID 37081165, 2023). "Analysis of a genome-wide RNAi screen found that LRIG1 is one of six genes which rank in the top 1% (out of 17,080 genes) whose knockdown promotes cancer cell proliferation, across 43 different cancer cell lines." (PMID 35440669, 2022). "An alternative approach is to restore endogenous LRIG1 expression, although this requires greater insight into mechanisms that silence LRIG1 in cancer." (PMID 35440669, 2022). "Gain- and loss-of-function studies in cancer cell lines from lung, breast and liver indicate that LRIG1 modulates cancer cell proliferation." (PMID 34385275, 2022). "Several studies have demonstrated decreased expression of LRIG1 in cancer, including lung, breast and head and neck cancer, among others." (PMID 35440669, 2022). "Activation of LRIG1 by the dCas9 transactivation system significantly increased LRIG1 protein abundance, reduced site-specific methylation, and reduced cancer cell viability." (PMID 35440669, 2022). "In cancer, the roles of LRIG1 and LRIG3 should be re-evaluated in light of their functions as BMP sensitizers." (PMID 33469151, 2021). "The ectodomain of LRIG1 can be shed from cell surfaces and recombinant ectodomain can suppress cancer cell proliferation both in vitro and in vivo." (PMID 33947959, 2021). "The LRIG1 immunoreactivity was found in the cytoplasm of enterocytes as well as cancer cells of the analyzed tissues." (PMID 33461538, 2021).
cancer (continued). "Incidentally, LRIG1 is located at the chromosome band 3p14.3, the chromosomal region that is often found to be deleted in human cancers." (PMID 33893245, 2021). "EPHB3 expression was higher in CRCs than in normal mucosa and was associated with the intestinal stem cell markers EPHB2, OLFM4, LRIG1, and a proposed cancer stem cell marker, CD44." (PMID 32294981, 2020). "Next, we probed the role LRIG1 played in anti-cancer activity of ISL, we showed that ISL induced cell apoptosis was reversed when LRIG1 was knocked down, the expression level of pro-apoptotic genes(C-PARP, Bax, C-caspase-3) was enhanced." (PMID 30081934, 2018). "Having high LRIG1 expression was significantly correlated with superior cancer-specific survival in univariate and multivariate analyses." (PMID 28841699, 2017). "To date, no previous study has reported such a distinctive expression pattern of LRIG1, indicating that LRIG1 is potentially a novel neoplastic transformation marker that distinguishes benign from malignant tumors in human OSSN." (PMID 24709893, 2014). "Most of what is known about Lrig function has come from analysis of Lrig1, which is downregulated in several human cancers." (PMID 24086156, 2013). "All of these studies proved that increased expression of LRIG1 worsens the prognosis of cancer." (PMID 38790164, 2024). "Furthermore, exploration using the AmiCa web tool indicated that LRIG1 gene expression was elevated compared to 17 other cancers included in the database, emphasizing its potential as a distinctive biomarker across multiple cancer types." (PMID 38790164, 2024). "This suggests that manipulating LRIG1 expression may offer a novel therapeutic approach for cancers driven by the aberrant EGFR signaling." (PMID 38790164, 2024). "In previous studies, Lrig1 has been known to be involved in EGFR degradation in cancer cells." (PMID 37666819, 2023). "Leucine-rich repeats and immunoglobulin-like domains protein 1 (LRIG1) is important in cancer development as it negatively regulates the epidermal growth factor receptor (EGFR); however, the mechanism responsible for this particular risk SNP and its potential effect on LRIG1 are not known." (PMID 37185361, 2023). "Since persistence of LRIG1 expression is associated with superior patient survival across cancer types and because prior studies have shown that LRIG1 is epigenetically and transcriptionally regulated, we reasoned that transcriptional reactivation of LRIG1 expression in cancer cells was feasible." (PMID 35440669, 2022). "Our findings suggest that CRISPR-mediated targeted activation may be a feasible way to restore LRIG1 expression in cancer." (PMID 35440669, 2022). "Genome-based CRISPR/dCas9 activation allows precise and stable editing of the epigenome with high efficiency, which could be harnessed for precision medicine and treatment of LRIG1-defincient cancers." (PMID 35440669, 2022). "A decrease in Lrig1 has emerged as an indicator of worse prognosis in several cancer types." (PMID 36420140, 2022). "We next examined the functional impact of reactivation of LRIG1 on the viability of cancer cells." (PMID 35440669, 2022). "As LRIG1 copy number variations are rare in cancer, we hypothesised that epigenetic silencing of LRIG1 would be prevalent and explain its more significant loss in ER-negative and basal/TNBC disease." (PMID 35440669, 2022). "LRIG1 downregulation in cancer is widespread, with a recent study reporting “no to low” LRIG1 expression in cell lines from 22 different cancer types, and patient samples from seventeen different cancer types." (PMID 35440669, 2022). "Also, while nuclear LRIG1 has been reported in several cancer forms and in keratinocytes previously, the nuclear localization has not been validated." (PMID 33947959, 2021). "Our data indicated that the drugs stimulating LRIG1 activity such as LRIG1-specific agonistic mAbs (monoclonal antibodies) could be a novel strategy for cancer therapy." (PMID 31358815, 2019).
cancer (continued). "Aberrant reduction in LRIG1 has been confirmed in several cancers." (PMID 30487162, 2019). "In silico analyses of The Cancer Genome Atlas data sets revealed consistent correlations between the expression of the transcripts encoding LRIG1 and its interactors ZBTB16 and PTPRK and inverse correlations between the transcripts encoding LRIG1 and GLRX3." (PMID 29317492, 2018). "When metagene 19 is active, LRIG1 results in inhibition of cancer cell growth." (PMID 28727543, 2018). "Additionally, PTPRK and LRIG1 expression was consistently correlated in a wide range of cancer types and normal tissues." (PMID 29317492, 2018). "RAB4A is involved in the recycling of early endosomes and has been implicated as an important determinant of the invasiveness of cancer cells, thereby providing a possible molecular link between LRIG1 and its apparent metastasis-suppressing function (45, –, 48)." (PMID 29317492, 2018). "And the anti-cancer effect of ISL is mitigated when LRIG1 is silenced in vivo and in vitro." (PMID 30081934, 2018). "LRIG1 expression has prognostic significance in various human cancers." (PMID 26632716, 2015). "Thus, and to the best of our knowledge, the findings of this study show for the first time that LRIG1 is a potential novel neoplastic transformation marker that distinguishes benign from malignant tumors in human OSSN." (PMID 24709893, 2014). "Soluble ectodomains of LRIG1 are reportedly sufficient to inhibit the growth of cancer cells by attenuating EGFR activity, and more recently, a study showed that the LRIG1 ectodomain can be naturally shed and can function as a non-cell-autonomous regulator of EGFR signaling." (PMID 24709893, 2014). "Moreover, the absence of any obvious morphogenetic or gross cochlear patterning defects argues against the idea that Lrig1 and Lrig2 act redundantly to control any of the major signaling pathways, consistent with their distinct effects in vitro and in cancer." (PMID 24086156, 2013). "Its expression is downregulated in a variety of human cancer supporting the hypothesis that decreased expression of LRIG1 unleashes EGFR signaling, which might contribute to tumorigenesis." (PMID 22589739, 2012). "Moreover, the LRIG1 gene was shown to be downregulated in 12 cancers." (PMID 38790164, 2024). "Notably, in the presence of cutaneous lesions due to HPV or derived carcinoma, unsorted Lrig1+ cells (human interfollicular epidermal stem cells) demonstrated an increased colony-forming efficiency consistent with an expansion in keratinocyte stem cell numbers." (PMID 38732382, 2024). "The significant reduction in cancer cell viability suggests that LRIG1 reactivation via CRISPR/dCas9 may have an impact on TNBC growth, however, future studies will be required to assess biological relevance in more disease-relevant models such as patient-derived organoids and in vivo mouse models." (PMID 35440669, 2022). "Although the precise mechanism of LRIG1 downregulation in cancer cells remains unclear, the findings of a recent study demonstrated that LRIG1 forms a ternary complex between LRIG1, E-cadherin, and EGFR, which upon cell-to-cell contact negatively regulates EGFR signaling." (PMID 24709893, 2014). "Leucine-rich repeats and immunoglobulin-like domains 1(LRIG1) is a transmenbrane leucine-rich repeat and immunoglobulin(Ig)-like domain-containing protein, whose transcript is located at chromosome 3p14.3, a region frequently deleted in various types of human cancers." (PMID 24314030, 2013). "In oral SCC cells, downregulation of leucine-rich repeats and immunoglobulin-like domains 1 (LRIG1) induced the activation of EGFR-mediated SphK1 signaling to promote extracellular matrix (ECM) remodeling and cancer cell progression." (PMID 33465049, 2021). "A total of 10 genes that were disrupted or within breakpoint‐associated TAD structures were classified as known (FHIT, FLCN, NCOA4, and RET) or candidate cancer genes (LLGL1, LRIG1, LYRM9, RASGEF1A, ST3GAL6, and TMEM199)." (PMID 31943436, 2020).
cancer (continued). "Analysis demonstrated two known cancer genes (NCOA4 and RET) and a further five candidate cancer genes (LLGL1, LRIG1, LYRM9, ST3GAL6, and TMEM199) were within breakpoint‐containing TADs." (PMID 31943436, 2020). "To further test the robustness of this result, we analyzed a 770 gene “pan-cancer” panel together with 31 AOM-DSS-induced (23 FFPE and 8 frozen) and 25 Apcfl;Lrig1-CreERT2 (12 FFPE and 13 frozen) Oct1 wild-type samples." (PMID 31059499, 2019). "Calcitriol increases the expression of stemness-related genes, such as the leucine-rich repeat-containing G protein-coupled receptor 5 (LGR5), SMOC2, LRIG1, MEX3A, MSI1, and PTK7, attenuating the transformation into cancer stem cells, and, therefore, impacts tumorigenesis at a very early stage." (PMID 36364774, 2022). "LRIG1 has no or low expression in more than 80% across all the cancer cell lines (#13) and different cancer types." (PMID 31358815, 2019). "Although these studies did not compare benign and malignant tumors, these findings imply an anti-metastatic role of LRIG1 and thus support our suggestion." (PMID 24709893, 2014). "Overall, these findings position LRIG1 as a negative feedback attenuator of signaling pathways mediated by receptor tyrosine kinases, highlighting its potential importance in controlling cell fate and behavior, especially in the context of cancer." (PMID 38790164, 2024). "However, EGF signaling must be controlled discreetly, since ablation of leucine rich repeats and immunoglobulin like domains 1 (Lrig1), an ISC marker and negative regulator of EGFR, induces ISC expansion or even duodenal adenomas and superficially invasive carcinomas in mice." (PMID 36969191, 2023). "As the AR−/lo PCa such as LAPC9-CRPC is greatly enriched in cancer stem cells and frequently overexpresses stemness factors such as NANOG69, it is tempting to speculate that in such tumors/clones, stemness factors predominantly regulate LRIG1." (PMID 31792211, 2019).
infection (2 papers, 2013 to 2024). The state of being infected such as from the introduction of a foreign agent such as serum, vaccine, antigenic substance or organism. "This population of KLF5+, Lrig1+ cells increased significantly in H. pylori-infected compared to uninfected tissues at both 4 weeks and 8 weeks post-infection." (PMID 23372710, 2013). "The induction of Lgr5 was fairly specific, as other gastric stem cell markers, such as Sox2, Troy, Runx1, Lrig1, and others were not induced as a consequence of infection; an exception was Ascl2, the expression of which mirrored that of Lgr5." (PMID 39191487, 2024).
benign tumors (1 paper, 2014). "Within the limitations of the small sample size, the findings of this study show that LRIG1 expression is downregulated in human conjunctival SCC, and inversely, upregulated in benign tumors, as compared to normal tissue." (PMID 24709893, 2014).
prostate (1 paper, 2019). "Here, the authors show that androgen receptor directly transactivates LRIG1 which then antagonises ERBB signalling and c-Myc expression to inhibit prostate tumorigenesis." (PMID 31792211, 2019).
LRIG1 also shares sentences with these, for which no sentence is quoted: adenocarcinoma (4 papers); head and neck cancer (3); GI tumors (2); metabolic disease (2); Alzheimer disease (1); B-cell lymphoma (1); brain cancer (1); cervical intraepithelial neoplasia (1); cholangiocarcinoma (1); colon adenocarcinoma (1); emphysema (1); heart failure (1); Hypercholesterolemia (1); ischemic stroke (1); leprosy (1); lupus nephritis (1); lymph node metastasis (1); Merkel cell carcinoma (1); nevus (1); periodontitis (1); pilomatricomas (1); porocarcinomas (1); renal carcinoma (1); squamous cell lung carcinoma (1); thymoma (1); thyroid cancer (1); vascular cancer (1).